DGCR5 (DiGeorge syndrome critical region gene 5)
Synonyms: NCRNA00037; LINC00037; X91348; DGS-A; POM121L5P; DGS-B; RIP; DGCR10; DGCR9
Gene: Long non-coding RNA gene on chromosome 22 (18,969,692 to 19,031,242, forward strand). Ensembl gene ENSG00000273032.
Diseases named in the same sentence as DGCR5 in open-access papers:
DGCR5 is named in the same sentence as 42 diseases in open-access papers, as found by Europe PMC text mining. Sharing a sentence is not in itself a finding about the gene and the disease. The quoted sentences say what the papers report.
lung carcinoma (12 papers, 2017 to 2023). "DGCR5 has been associated with the prognosis of both lung cancer and HCC, and in our study, we found that a lower DGCR5 level correlated with a poor prognosis in patients with PDAC." (PMID 29207609, 2017). "The association between lncRNA DGCR5 and lung cancer had been found." (PMID 31775885, 2019). "Hsa-miR-22-3p serves as the target of DGCR5, reducing its expression to inhibit the occurrence of lung cancer." (PMID 35011220, 2022). "It is reported that DGCR5 suppresses lung cancer cell proliferation, migration, and invasion by targeting miR-1180 and by interacting with miR-873-5p to regulate the tumor suppressor candidate 3 (TUSC3)." (PMID 34322486, 2021). "It is reported that DGCR5 expression in lung cancer patients and their sera are either upregulated or downregulated." (PMID 34322486, 2021). "In lung cancer, DGCR5 bound to miR-1180 to suppress AKT, GSK-3β, and β-catenin expression, therefore suppressing the capacity of H520 and H1299 lung cancer cells to proliferate, migrate and invade." (PMID 33085646, 2020). "In a study conducted on patients with lung cancer, DGCR5 was found to be significantly lower in the neoplastic tissues than in the non-neoplastic tissues." (PMID 31319040, 2020). "For further validation of DGCR5’s role in lung cancer, A549 cells were transfected with DGCR5 control siRNA (control group) and DGCR5 siRNA1‐4 (experimental groups)." (PMID 29790668, 2018). "Upregulation of DiGeorge syndrome critical region gene 5 (DGCR5) predicts better lung squamous cell carcinoma prognosis; therefore, we explore the role of DGCR5 in lung cancer in our present study." (PMID 29790668, 2018). "In conclusion, these data suggested the involvement of DGCR5 in the cell proliferation of lung cancer cells." (PMID 29790668, 2018). "As we observed a negative correlation between DGCR expression with metastasis in patients with lung cancer, we next focus on the role of DGCR5 on lung cell migration and invasion." (PMID 29790668, 2018). "DGCR5 was first reported to be downregulated in Huntington’s disease, and other studies have demonstrated that DGCR5 plays a role in the progression of many cancers including lung cancer and hepatocellular carcinoma." (PMID 29207609, 2017). "In addition to this, DGCR5 downregulation is found to significantly correlate with the poor prognosis of lung cancer patients and the aggressive clinical features in gastric cancer patients." (PMID 34322486, 2021). "However, other studies demonstrate a tumor-suppressive role of DGCR5 in lung cancer, gastric cancer, bladder cancer, and cervical cancer." (PMID 34322486, 2021). "Previous studies reported that DGCR5 plays an important role in the development of lung cancer." (PMID 33924522, 2021). "As in lung cancer, DGCR5 may also play a tumor-suppressive role in breast cancer cells and contribute to the antiproliferative effect of CCT137690." (PMID 31319040, 2020). "DGCR5 was demonstrated to be a tumor suppressor gene in both lung cancer and HCC, and in accordance with this finding, our study found that DGCR5 could inhibit the proliferation and migration of PDAC cells." (PMID 29207609, 2017). "CRNDE and DGCR5 (DiGeorge Syndrome Critical Region Gene 5) lncRNAs, highly expressed in EGFR‐TKI‐resistant lung cancer cells, bind eukaryotic translation initiation factor 4A3 (EIF4A3) in an overlapping manner." (PMID 37042179, 2023). "LncRNAs are overexpressed in a variety of cancers, including lncRNA DGCR5 and DANCR in lung cancer, lncRNA H19 in melanoma, and lncRNA TUG1 in ovarian cancer." (PMID 34131102, 2021).
glioma (11 papers, 2020 to 2024). A benign or malignant brain and spinal cord tumor that arises from glial cells (astrocytes, oligodendrocytes, ependymal cells). "In previous publications, DGCR10 (also known as DGCR5) acted as a tumor-suppressive factor in glioma, consistent with our findings, which upregulated significantly inhibited glioma cell proliferation, migration, and invasion, whereas promoted apoptosis." (PMID 37264314, 2023). "Immune-related lncRNA (DiGeorge syndrome critical region gene 5 (DGCR5) expression is downregulated in glioma, and high expression independently predicts better prognosis in glioma patients." (PMID 36032137, 2022). "According to another study, the expression of lncRNA DiGeorge syndrome critical region gene 5 (DGCR5) was decreased in low-grade glioma and GBM tissues, and DGCR5 is deeply related to the regulation of several immune responses proven by TCGA and CGGA datasets." (PMID 34202078, 2021). "Herein, miR-21 and miR-23a, two significantly increased miRNAs in glioma, were both predicted to be downstream targets of lncRNA DGCR5." (PMID 33085646, 2020). "Since microvascular proliferation glioma is the most malignant and invasive, these data indicated that lncRNA DGCR5 expression continued to be downregulated with tumor progression." (PMID 33085646, 2020). "In vivo experiments in an orthotopic implanted xenograft model further confirmed that lncRNA DGCR5 acts as a tumor-suppressor to inhibit glioma tumor growth." (PMID 33085646, 2020). "In conclusion, lncRNA DGCR5 suppresses the capacity of glioma cells to migrate and to invade via miR-21/Smad7, and it inhibits the proliferation and enhances the apoptosis of glioma cells through miR-23a/PTEN." (PMID 33085646, 2020). "To validate the specific effect of lncRNA DGCR5 on glioma cells, we first constructed the coexpression network consisting of DGCR5 and its negatively-correlated genes according to TCGA data, REMBRANDT data, and GSE4290." (PMID 33085646, 2020). "More importantly, miR-21 or miR-23a overexpression significantly attenuated the involvement of lncRNA DGCR5 overexpression in the capacity of glioma cells to proliferate, migrate, invade, and/or undergo apoptosis in these cells." (PMID 33085646, 2020). "Based on these findings, lncRNA DGCR5 was demonstrated to block EMT in glioma cells, thereby acting as a tumor suppressor." (PMID 33085646, 2020). "LncRNA DGCR5 overexpression significantly inhibited the capacity of DNA synthesis, invasion and migration in glioma cells, whereas it enhanced the apoptosis rate of glioma cells." (PMID 33085646, 2020). "According to a series of online data, lncRNA DGCR5 expression was found to be significantly downregulated in glioma, especially in samples from advanced stages." (PMID 33085646, 2020). "LncRNA DGCR5 overexpression significantly inhibited the capacity of glioma cells to proliferate, migrate, and invade, whereas promoted the apoptosis of glioma cells." (PMID 33085646, 2020). "In conclusion, lncRNA DGCR5 suppresses the capacity of glioma cells to migrate and invade via miR-21/Smad7, whereas it inhibits the proliferation and enhances the apoptosis of glioma cells through miR-23a/PTEN." (PMID 33085646, 2020). "In summary, the DGCR5/miR-23a axis affects glioma cell proliferation and apoptosis through PTEN/PI3K/AKT." (PMID 33085646, 2020). "Herein, we found that NF-κB1 inhibited the expression of NF-κB1 RE in glioma cells via direct binding to the NF-κB1 RE in the lncRNA DGCR5 promoter region." (PMID 33085646, 2020). "Herein, we identified lncRNA DGCR5 as a downregulated lncRNA in glioma that was negatively regulated by NF-κB1 in an NF-κB1 RE-dependent manner." (PMID 33085646, 2020). "To further investigate the suppressive effects of lncRNA DGCR5 on the proliferation, migration, and invasion of glioma cells, we analyzed TCGA data to identify miRNAs that were negatively correlated with DGCR5." (PMID 33085646, 2020).
glioma (continued). "We found that several lncRNAs, namely, AL606760.2, H19, MALAT1, PVT1 and SBF2-AS1 may function as glioma risk factors, whereas AC068643.1, AC079228.1, DGCR5, FAM13A-AS1, HAR1A and WDFY3-AS2 may have protective effects." (PMID 36819921, 2023). "In addition, the downregulation of DGCR5 was mainly responsible for the poor prognosis of glioma patients." (PMID 34202078, 2021). "According to all these online data, we hypothesized that lncRNA DGCR5 might play a protective role against glioma progression." (PMID 33085646, 2020). "In glioma cell lines, DGCR5 negatively regulated the expression levels of miR-21 and miR-23a." (PMID 33085646, 2020). "In summary, the DGCR5/miR-21 axis affects glioma cell migration, invasion, and EMT through Smad7." (PMID 33085646, 2020). "DGCR5 overexpression markedly enhanced PTEN protein levels in the two glioma cell lines." (PMID 33085646, 2020). "Then, DGCR5 expression was determined in NF-κB1 or si-NF-κB1 transfected glioma cells." (PMID 33085646, 2020). "In summary, lncRNA DGCR5 might inhibit the capacity of glioma cells to proliferate, migrate, and invade, thus exerting a tumor-suppressive effect." (PMID 33085646, 2020). "We identified lncRNA DGCR5 as a downregulated lncRNA in glioma that could be negatively regulated by NF-κB1 through direct binding." (PMID 33085646, 2020). "Thus, DGCR5 might exert its effects on glioma cells through miR-21 and miR-23a and their respective targets." (PMID 33085646, 2020). "Therefore, we speculated that the DGCR5/miR-23a axis might affect PTEN to act on glioma cell proliferation and apoptosis." (PMID 33085646, 2020). "Thus, it is reasonable to hypothesize that lncRNA DGCR5 might play a role in glioma progression, possibly by regulating EMT." (PMID 33085646, 2020). "Thus, we investigated whether the DGCR5/miR-21 axis affects Smad7 to act on glioma cell migration and invasion." (PMID 33085646, 2020). "Various lncRNAs were found to be aberrantly expressed in glioma, such as lncRNA PVT1, lncRNA BCYRN1 and lncRNA DGCR5." (PMID 38730506, 2024). "For example, although DGCR5 levels were unrelated to WHO malignancy grade in glioma, they were more downregulated in IDH-wildtype glioma than in IDH-mutant glioma." (PMID 36819921, 2023). "A role of lncRNAs in even pediatric gliomas’ EMT has been suggested and lncRNA DGCR5 can inhibit EMT in such gliomas where it is down-regulated during the disease progression." (PMID 34485294, 2021). "A total of 18 genes were significantly negatively correlated with DGCR5, including GNAI3, VIM, ITGB1, HIF1A, and HDAC1, all of which are critical factors affecting glioma development." (PMID 33085646, 2020). "Furthermore, DGCR5 increased the levels of Smad7 and phosphatase and tensin homolog (PTEN) by sponging miR-21 and miR-23a, respectively, in glioma cells." (PMID 36819921, 2023). "The lncRNA DGCR5 is related to immune-related biological processes and simultaneously strongly negatively correlated with WHO grade of malignancy in glioma suggesting a role in inflammatory activities or immune checkpoints in glioma." (PMID 33126510, 2020). "According to TCGA data, the expression of lncRNA DGCR5 was reduced in proneural glioma, neural glioma, mesenchymal glioma, and classical glioma, compared with noncancerous (normal) tissue samples." (PMID 33085646, 2020). "Similarly, overexpression of lncRNA DGCR5 in U251-MG and SHG44 cells dramatically increased the capacity of glioma cells to proliferate, migrate, and invade, suggesting that lncRNA DGCR5 exerted a tumor-suppressive effect on glioma." (PMID 33085646, 2020).
Huntington disease (9 papers, 2012 to 2023). Huntington disease (HD) is a rare neurodegenerative disorder of the central nervous system characterized by unwanted choreatic movements, behavioral and psychiatric disturbances and dementia. "We also found that DGCR5, a noncoding brain-enriched gene previously known as a biomarker for Huntington’s disease, is highly associated with DD." (PMID 37486921, 2023). "DGCR5 (Digeorge syndrome critical gene 5, also known as linc00037) is a lncRNA downregulated in Huntington’s disease neurodegeneration, which has also been implicated in cancer progression." (PMID 33777808, 2021). "LncRNA DiGeorge syndrome critical region gene 5 (DGCR5) was first identified in Huntington's disease." (PMID 33613108, 2021). "However, RNA expression from this gene is down-regulated in certain diseases: Huntington's disease, where DGCR5 is regulated by the transcriptional repressor REST and hepatocarcinoma." (PMID 29668722, 2018). "DiGeorge syndrome critical region gene 5 (DGCR5), which is also known as Linc0037, was first reported to be downregulated in Huntington’s disease but has also been reported to be downregulated in PDAC." (PMID 29207609, 2017). "Recently it was found that repression of HAR1F by REST leads to its decreased expression in the striatum of Huntington’s disease, and that REST also interacts with DGCR5 and TUG1 lncRNAs leading to DiGeorge syndrome and Huntington’s disease." (PMID 22811697, 2012). "Johnson (2012) extended these investigations and confirmed that both TUG1 and NEAT1 are significantly up-regulated in Huntington’s disease brains, whereas MEG3 and DGCR5 showed decreased expression." (PMID 22811697, 2012).
gastric cancer (6 papers, 2020 to 2022). A primary or metastatic malignant neoplasm involving the stomach. "In gastric cancer, lncRNA DGCR5 is known for its function as a ceRNA (competing endogenous RNA) of PTEN and BTG1 through miR-23b to inhibit the capacity of gastric cancer cells to proliferate, invade, and migrate while promoting the apoptosis of these cells." (PMID 33085646, 2020).
hepatocellular carcinoma (6 papers, 2017 to 2022). A malignant tumor that arises from hepatocytes. "KLF14 is regulated as a target gene of lncRNA DGCR5 to inhibit the progression of hepatocellular carcinoma (HCC)." (PMID 35570248, 2022).
pancreatic cancer (6 papers, 2017 to 2023). "Forced up-regulation of DGCR5 in pancreatic cancer cells leads to the down-regulation of miR-27a-3p." (PMID 34827663, 2021). "To determine the possible role of DGCR5 in the response of pancreatic cancer cells to 5-FU, we generated 5-FU-resistant HPAC and PANC-1 cells." (PMID 29207609, 2017). "Overall, these results imply that DGCR5 is involved in the regulation of the response of pancreatic cancer cells to 5-FU and in the reduction in chemoresistance of pancreatic cells to 5-FU." (PMID 29207609, 2017). "The expression level of DGCR5 in 5-FU-resistant HPAC and PANC-1 cells was significantly reduced compared with that in parental cells, which indicates that DGCR5 may be involved in the regulation of the response of pancreatic cancer cells to 5-FU response." (PMID 29207609, 2017). "Similarly, DGCR5 was proved that can promote pancreatic cancer by targeting miR-3163/TOP2A." (PMID 36003146, 2022). "However, the biological role and molecular mechanism of DGCR5 in pancreatic cancer (PC) remains largely unknown." (PMID 33613108, 2021). "LINC01111/miR-3924, LINC01963/miR-641, DGCR5/miR-27a-3p, GAS5/miR-32-5p, and LINC00261/miR-23a-3p axes are examples of the latter type of lncRNA/miRNA interactions in the context of pancreatic cancer." (PMID 34827663, 2021).
schizophrenia (6 papers, 2016 to 2023). A major psychotic disorder characterized by abnormalities in the perception or expression of reality. "For schizophrenia, DGCR6 and PRODH are well-known candidate genes, and DGCR5 is a long non-coding RNA gene with a high score for causing schizophrenia." (PMID 37486921, 2023). "Among the top 40 genes associated with developmental delay, DGCR6, PRODH, DGCR5, and ZDHHC8 are potential candidates for involvement in DiGeorge syndrome pathology and schizophrenia." (PMID 37486921, 2023). "Another potential genetic factor for schizophrenia is DGCR5, which is a long non-coding RNA (lncRNA) with a high score for causing schizophrenia." (PMID 37486921, 2023). "Refseq genes in this region include FAM230F, DGCR6, PRODH, DGCR5, with pathogenic PRODH variants associated with autosomal recessive hyperprolinemia type I or autosomal susceptibility to schizophrenia." (PMID 34938854, 2021). "This region spanned the DiGeorge syndrome critical region gene 5 and 6 (DGCR5 and DGCR6) as well as the proline dehydrogenase 1 (PRODH) gene implicated in schizophrenia and hyperprolinemia type 1." (PMID 26933844, 2016).
esophageal squamous cell carcinoma (4 papers, 2022 to 2025). Esophageal squamous cell carcinoma (ESCC) is a type of esophageal carcinoma (EC) that can affect any part of the esophagus, but is usually located in the upper or middle third. "For instance, esophageal squamous cell carcinoma (ESCC) is associated with a poor prognosis when the lncRNA DGCR5 is highly expressed." (PMID 40129920, 2025). "Long non-coding RNA (lncRNA) DiGeorge syndrome critical region gene 5 (DGCR5) was associated with the stabilization of SRSF1, which resulted in an increased level of MCL-1L in esophageal squamous cell carcinoma." (PMID 39695189, 2024).
laryngeal carcinoma (4 papers, 2020 to 2023). Carcinoma that arises from the laryngeal epithelium. "The tumor-promoting effects of DGCR5 in laryngeal cancer cells were validated by downregulating DGCR5." (PMID 37190145, 2023). "In laryngeal cancer, lncRNA DGCR5 upregulated radioresistance through miR-506/Wnt pathway, and Wnt pathway is one of the key cascades that regulate caner development and stemness." (PMID 35600868, 2022). "DGCR5 is found to promote cell proliferation and cancer stem cell properties and contribute to the radioresistance in laryngeal carcinoma cells by sponging miR-506 and miR-195." (PMID 34322486, 2021). "For example, in laryngeal cancer, DiGeorge syndrome critical region gene 5 (DGCR5) can sponge miR-195 and miR-506, to induce CSCs-like characteristics in radioresistant tumor cells." (PMID 32122355, 2020). "DGCR5 promotes radioresistance and CSC proliferation for laryngeal cancer cells by sponging miR-195 and miR-506, respectively." (PMID 37190145, 2023).
lung squamous cell carcinoma (3 papers, 2018 to 2021). "However, DGCR5 expression was very low in papillary RCC, liver cancer, and lung squamous cell carcinoma and rarely detected in chromophobe RCC, prostate cancer, and colon cancer." (PMID 34322486, 2021).
lymph node metastasis (3 papers, 2018 to 2021). "Univariate Cox regression analysis showed that TNM stage (P = 0.045), lymph node metastasis (P = 0.047), and DGCR5 expression (P = 0.003) were significantly associated with the prognosis of ESCC patients." (PMID 34099633, 2021). "Covariates included in Cox proportional hazards model are gender, age, TNM stage, lymph node metastasis, invasion range, and DGCR5 expression." (PMID 34099633, 2021). "Then, we examined that elevated expression of DGCR5 was positively correlated with deeper invasion range, more lymph node metastasis, and higher TNM stage." (PMID 34099633, 2021). "Meanwhile, the correlation between DGCR5 level and multiple clinicopathologic features (age, gender, lymph node metastasis, distant metastasis, and tumor size) was analyzed." (PMID 29790668, 2018). "Moreover, elevated DGCR5 expression was significantly associated with higher TNM stage, deep invasion range, more lymph node metastasis." (PMID 34099633, 2021).